SH2D1A (SH2 domain containing 1A)
Diseases named in the same sentence as SH2D1A in open-access papers:
SH2D1A is named in the same sentence as 68 diseases in open-access papers, as found by Europe PMC text mining. Sharing a sentence is not in itself a finding about the gene and the disease. The quoted sentences say what the papers report.
X-linked lymphoproliferative disease (48 papers, 2010 to 2025). X-linked lymphoproliferative disease is a hereditary immunodeficiency characterized, in the majority of cases, by an inadequate immune response to infection with the Epstein-Barr virus (EBV). "X-linked lymphoproliferative disease (XLP1), also known as Duncan disease, is an inborn error of immunity caused by mutations in the SH2D1A gene, affecting 1 in 1 million males." (PMID 39309261, 2024). "X-linked Lymphoproliferative Syndrome (XLP) results from mutations in the SH2D1A gene, affecting the regulation of immune responses to viral infections and often leading to reduced levels of immunoglobulins." (PMID 39712011, 2024). "In 1998, SH2D1A was discovered to be the gene mutated in X-linked lymphoproliferative disease (XLP)." (PMID 33936082, 2021). "X-linked lymphoproliferative disease (XLP1) is a combined immunodeficiency characterized by severe immune dysregulation caused by mutations in the SH2D1A/SAP gene." (PMID 34987501, 2021). "SH2D1A mutations have been causally implicated in X-linked lymphoproliferative syndrome 1 (XLP1, MIM: 308240)." (PMID 32081864, 2020). "In humans, mutations in SH2D1A (encoding for SAP) are causative of X-linked lymphoproliferative disease (XLP), an immune pathology characterised by an extreme sensitivity to Epstein Barr Virus infections." (PMID 29337666, 2018). "A delayed diagnosis can impact on prognosis if a patient has a life threatening disorder, such as presymptomatic males with X-linked lymphoproliferative syndrome (XLP) from SH2D1A or BIRC4 mutations." (PMID 27980540, 2016). "While defects in the gene SH2D1A were initially detected in patients with X-linked lymphoproliferative disease, known as XLP1, mutations in XIAP result in XLP2." (PMID 26581487, 2015). "A definitive diagnosis of X-linked lymphoproliferative disease is with mutation analysis for the SH2D1A and XIAP genes mutation." (PMID 24385755, 2013). "X-linked lymphoproliferative disease (XLP) is an immunodeficiency caused by mutations in the SH2D1A gene, which encodes a cytoplasmic component, SAP involved in a signalling pathway in certain populations of immune cells." (PMID 22069374, 2011). "Interestingly, in a child with a phenotypic characteristic of CVID and subsequent rapid development of non-Hodgkin’s lymphoma, the genetic diagnosis showed X-linked lymphoproliferative syndrome caused by a deletion in the SH2D1A gene." (PMID 36211402, 2022). "X-linked lymphoproliferative disease (XLP) was diagnosed in eight patients: four cases each of SH2D1A (XLP1) and XIAP (XLP2) variants." (PMID 41300767, 2025). "The X-linked lymphoproliferative diseases (XLP) caused by pathogenic variants of SH2D1A (XLP1) and XIAP (XLP2) can also present with HLH." (PMID 35601409, 2022). "Defects in Sh2d1a in humans causes X-linked lymphoproliferative disease (XLP), a disorder with high mortality characterized by the inability to clear infections and dysregulated T cell responses." (PMID 27223891, 2016). "Interestingly, a study showed a quarter of male patients with EBV-associated HLH may have mutations in the SH2D1A gene, which is traditionally associated with X-linked lymphoproliferative syndrome (XLPS) immunodeficient to EBV." (PMID 25757854, 2015). "In humans, mutations of SH2D1A are the cause of the immunodeficiency disease, X-linked lymphoproliferative disease (XLP) and it has been found in mice that SH2D1A is required for the proper functioning of the primary and secondary immunoglobulin responses." (PMID 24992587, 2014). "X-linked Lymphoproliferative Syndromes (XLP), arising from mutations in SH2D1A or XIAP genes, are characterized by fulminant Epstein-Barr virus (EBV) infection." (PMID 40674368, 2025). "SLAMF proteins interact with the protein product of SH2D1A (gene alias SAP), an IEI gene that causes X-linked lymphoproliferative syndrome (XLP1) characterized by severe EBV infections." (PMID 40761639, 2025).
X-linked lymphoproliferative disease (continued). "X-linked lymphoproliferative disease is a rare inherited immune disorder, caused by mutations or deletions in the SH2D1A gene that encodes an intracellular adapter protein SAP (Slam-associated protein)." (PMID 35677600, 2022). "Multiple PCR primers were designed for 6 genes using Ion AmpliSeqTM Designer; the SH2D1A and XIAP genes were included for distinguishing X-linked lymphoproliferative syndrome (XLP), which has a strong resemblance to HLH." (PMID 29783935, 2018). "One of the adaptors, SLAM-associated protein (SAP), encoded by the SH2D1A gene, is mutated in patients with X-linked lymphoproliferative syndrome." (PMID 22194822, 2011). "For instance, NKT cells may be absent in patients with some forms of X-linked lymphoproliferative disease (XLP), which is caused by mutations in the SH2D1A or XIAP genes." (PMID 20529312, 2010). "Congenital mutation or deletion of the SH2D1A gene encoding the SAP protein is well known to cause a primary immunodeficiency disease, immunodeficiency condition X-linked lymphoproliferative disease, indicating the biological importance of SAP function in T cell immune responses." (PMID 39886466, 2025). "X-linked lymphoproliferative syndrome (XLP) is a rare primary immunodeficiency disease that can be divided into two types: SAP deficiency (XLP1) and XIAP deficiency (XLP2), caused by mutations in the SH2D1A and XIAP genes, respectively." (PMID 31754776, 2020). "SH2D1A is a signaling lymphocytic activation molecule (SLAM)-associated protein (SAP), and it is one of the known disease-causing genes associated with immunodeficiency, which led to X-linked lymphoproliferative disease (XLP)." (PMID 28196537, 2017). "Moreover, patients with X-linked Lymphoproliferative disease (XLP), an immunodeficiency resulting from mutations in the SH2D1A gene which encodes SAP, harbor humoral defects characterized by hypogammaglobulinemia and reduced numbers of TFH." (PMID 27635407, 2016). "Disease-causing mutations in XIAP/BIRC4 were first described in 2006 in families with patients suffering from X-linked lymphoproliferative syndrome (XLP) with no mutations in the SH2D1A gene encoding SAP." (PMID 23818254, 2013). "In sharp contrast, we and others have showed that Sap−/− mice and patients with the immunodeficiency X-linked lymphoproliferative disease (XLP), that lack or express germline mutations in the SH2D1A gene, have almost no iNKT cells." (PMID 31569599, 2019). "Boys with mutations in the SH2D1A gene, which encodes SLAM-associated protein (SAP), have a complete absence of iNKT cells and develop X-linked lymphoproliferative disease (XLP), a form of severe and often fatal IM typically triggered by EBV infection." (PMID 26161082, 2015). "[The SAP gene (SH2D1A) is located on the X-chromosome, and the absence of SAP results in an X-linked lymphoproliferative disease, XLP, an immunodeficiency syndrome characterized by unstable T-B cell interactions, absence of germinal centers, and lack of isotype switched B cells." (PMID 38550577, 2024).
X-linked lymphoproliferative syndrome (26 papers, 2011 to 2025). "Other IEIs such as X-linked Hyper IgM syndrome (XHIM) and X-linked lymphoproliferative syndrome (XLP1) caused by pathogenic variants of CD40LG or SH2D1A, can occasionally present with antibody deficiency." (PMID 41324804, 2025). "The previous study indicated gene mutation of SH2D1A, which was thought to act as a negative regulator of immune cell activation, leaded to X-linked lymphoproliferative syndrome (XLP), in contrast, SHP-2 acted in positive manner to transduce signals from receptor protein tyrosine kinases." (PMID 29179441, 2017). "Other monogenic diseases that produce HLH are Chédiak-Higashi syndrome (LYST), Griscelli syndrome type 2 (RAB27A), Hermansky-Pudlak syndrome (AP3B1), X-linked lymphoproliferative syndrome (XLP)-1 (SH2D1A), and XLP-2 (XIAP)." (PMID 32076423, 2020). "A little under two decades ago, three independent research groups discovered an association between mutations in SH2D1A, the gene that encodes the intracellular adaptor protein SLAM-associated protein (SAP) and X-linked lymphoproliferative syndrome (XLP)." (PMID 26834746, 2016).
Immunodeficiency (16 papers, 2014 to 2025). Failure of the immune system to protect the body adequately from infection, due to the absence or insufficiency of some component process or substance. "X-linked lymphocytic proliferative disease type 1 (XLP1) is a primary immune deficiency caused by genetic alterations in the SH2D1A gene, exhibiting a wide variety of severe clinical phenotypes and high mortality." (PMID 40519929, 2025). "X‐linked lymphoproliferative (XLP) disease is a rare immunodeficiency caused by mutations in the SH2D1A/SAP or XIAP genes, respectively." (PMID 30565237, 2019). "X-linked lymph proliferative disease (XLP) is a human immunodeficiency caused by germ-line mutations in SH2D1A gene and characterized by an inability to respond appropriately to infections such as Epstein-Barr virus." (PMID 26452143, 2015). "Several immunodeficiency disorders associated with EBV lymphoproliferation have been described, including deficiency of ITK, XIAP, STK4, SH2D1A, and CD27." (PMID 27338827, 2016). "Notably, 2B4 and NTBA dysfunction was described to be associated with a severe form of immunodeficiency, the X-linked lymphoproliferative syndrome type 1 (XLP-1), caused by mutations in SH2D1A, the gene encoding the signaling lymphocyte activation molecule (SLAM)-associated protein (SAP)." (PMID 31316503, 2019).
lymphoma (9 papers, 2014 to 2024). A malignant (clonal) proliferation of B- lymphocytes or T- lymphocytes which involves the lymph nodes, bone marrow and/or extranodal sites. "Among IEI-associated genes,7,9NFKB2,26PIK3CD, STAT1,27PALB2, SH2D1A,28TNFRSF13B,10MSH6, CTLA4 genes had previously been reported in lymphoma or hematological malignancies genomic studies or are lymphoma susceptibility genes." (PMID 38547930, 2024).
primary immunodeficiency (7 papers, 2011 to 2025). "X-linked lymphoproliferative disease type 1 (XLP1) is a rare, often fatal primary immunodeficiency (PID) caused by mutations in the SH2D1A gene that result in an uncontrolled immune response to Epstein-Barr virus (EBV) infection." (PMID 40718244, 2025). "XLP1 is a primary immunodeficiency caused by mutations in SH2D1A, the gene encoding the signaling lymphocyte activation molecule (SLAM)-associated protein (SAP)." (PMID 31231370, 2019). "X-linked lymphoproliferative disease (XLP) is a primary immunodeficiency caused by mutations in SH2D1A which encodes SAP." (PMID 22069374, 2011). "X-linked lymphoproliferative disease type 1 (XLP1), an X-linked recessive genetic disorder, is associated with primary immunodeficiency due to genetic alterations of the SH2D1A gene encoding the signaling lymphocyte activation molecule (SLAM)-associated protein (SAP)." (PMID 40519929, 2025). "X-linked lymphoproliferative disease (XLP) is an inherited primary immunodeficiency caused by mutations in SH2D1A, which encodes the cytoplasmic adaptor protein SLAM-associated protein (SAP)." (PMID 22069374, 2011). "In five patients we detect a primary immunodeficiency or enteropathy, with clinical consequences (XIAP, CYBA, SH2D1A, PCSK1)." (PMID 32081864, 2020).
autoimmune disease (5 papers, 2014 to 2025). A disorder resulting from loss of function or tissue destruction of an organ or multiple organs, arising from humoral or cellular immune responses of the individual to their own tissue constituents. "Analysis of the mechanism of humoral immune memory originating from the discovery of the XLP-1-causing gene SH2D1A might lead to the development of new treatments of autoimmune diseases related to this virus." (PMID 36146707, 2022).
lupus (5 papers, 2016 to 2024). "In this case, two other possible diseases have been noted considering that SH2D1A mutation could involve in rheumatoid arthritis (RA) and systemic lupus erythematosus, but both of these diseases were excluded." (PMID 28196537, 2017). "Studies using knockout mice deficient in SLAM family receptors and SLAM-associated protein (SH2D1A) have shown that these molecules play an important role in T-cell-mediated help for humoral immunity a key process in lupus pathogenesis." (PMID 28387859, 2017). "In addition, the gene expression of sh2d1a, map3k1, spn and stat5b was enhanced after NaCl treatment, consistent with the findings in lupus CD4+T cells." (PMID 27325182, 2016).
lymphoproliferative disorders (5 papers, 2019 to 2025). "The pathogenic SH2D1A mutation had been reported in three unrelated families; affected males presented with fulminant infectious mononucleosis or lymphoproliferative disorders." (PMID 33329693, 2020). "Nearly 58% FHL cases are reported to harbour mutations in PRF1 gene (located at 10q22.1) that alters the normal function of perforin; whereas 40–60% of all X-linked lymphoproliferative disorders harbour mutation in SLAM-associated protein (SAP) regulating gene SH2D1A (located at Xq25)." (PMID 30849948, 2019). "These genes include HEXA (Tay-Sachs disease), CDKN1B (Neoplasia), GATA1 (Thrombocytopenia, Thalassemia), and SH2D1A (Lymphoproliferative syndrome)." (PMID 38033082, 2023). "After no candidate genes were identified by ES in a patient with lymphoproliferative syndrome, X-linked, 1 (XLP1; OMIM: #308240), an extended ES analysis of the SH2D1A identified breakpoints in exon 2 and intron 2 which were further validated to be a CGR including two deletions and one inversion." (PMID 36672937, 2023).
B cell lymphomas (3 papers, 2014 to 2020). "Yet, the observation that 5 of 158 males presenting with B-cell NHL (3.2%) had SH2D1A mutations raises the issue of prospective screening for XLP-1 in males with B-cell lymphoma." (PMID 24795715, 2014). "A SH2 domain containing 1A gene mutation in pediatric patients can regulate B-cell lymphoma." (PMID 31480149, 2020).
Arthritis (2 papers, 2018 to 2022). Inflammation of a joint. "During the course of our investigation, we cloned the SH2D1A gene that is critically involved in immune protection against EBV and applied humanized mice to generate a mouse model of EBV-induced RA-like arthritis." (PMID 36146707, 2022).
Autoimmunity (2 papers, 2017 to 2025). The occurrence of an immune reaction against the organism's own cells or tissues. "Conversely, by suppressing SH2 domain containing 1A (SH2D1A) and GPRC5A, miR‐31 promotes Th1 cytokine transcription but suppresses Treg generation, thus promoting autoimmunity in sepsis and experimental autoimmune encephalomyelitis." (PMID 40068094, 2025).
IgA nephropathy (2 papers, 2021 to 2022). "Before its identification as the cause of XLP-1, we had independently cloned a full-length SAP/SH2D1A cDNA (GenBank: AB586694.1) from mRNAs isolated from peripheral leukocytes of a patient with IgA nephropathy, which is also known as EBV-related disease." (PMID 36146707, 2022). "The SAP gene (SH2D1A) was first cloned from patients with IgA nephropathy in 1995, however its function was initially unknown and the work was not published until years later." (PMID 33936082, 2021).
colitis (1 paper, 2023). Inflammation of the colon. "The single case of IL-21 deficiency presented with recurrent sinopulmonary infections and early onset colitis, while ∼50% of patients with XL lymphoproliferative disease due to SH2D1A mutations (encoding SAP) have recurrent infections and impaired vaccine responses." (PMID 37273190, 2023).
dysgammaglobulinemia (1 paper, 2025). An immunologic deficiency state characterized by selective deficiencies of one or more, but not all, classes of immunoglobulins. "Furthermore, this SH2D1A mutation prevents the in vitro generation of plasmablasts, contributing to dysgammaglobulinemia." (PMID 41472689, 2025).
hepatocellular carcinoma (1 paper, 2023). A malignant tumor that arises from hepatocytes. "However, the functions of SH2D1A in hepatocellular carcinoma (HCC) have not been reported." (PMID 37858067, 2023).
liver failure (1 paper, 2020). A liver disease characterized by the liver losing or has lost all of its function. "The genetic diagnosis of SH2D1A deficiency was confirmed by the XLP1-specific extraintestinal complications of EBV-driven disease and liver failure." (PMID 32081864, 2020).
Mycobacterium infection (1 paper, 2021). Infections with bacteria of the genus Mycobacterium. "The role of the remaining 7 genes (CD2, CD6, CD247, ZAP70, CD3D, SH2D1A, and CD3E) in T-cell signaling and modulation of host immune responses in mycobacterium infections is also supported." (PMID 35198572, 2021).
pancreatic cancer (1 paper, 2021). "Our analyses revealed that the immune-related genes CCR4, CD19, TNFSF8, SH2D1A, ICOS, IGKV1D-39, and TNFRSF17 may be implicated in the immunophenotyping of pancreatic cancer." (PMID 34737763, 2021). "The results revealed seven immune-related genes (CCR4, CD19, TNFSF8, SH2D1A, ICOS, IGKV1D-39, and TNFRSF17) could potentially influence the immunophenotyping of pancreatic cancer." (PMID 34737763, 2021).
T-cell lymphoma (1 paper, 2014). "We identified two patients in our study with X-linked SH2D1A gene sequence abnormalities, one of them was a heterozygous female carrier (P12) who experienced onset of HLH clinical symptoms at age 18, associated with T-cell lymphoma." (PMID 25233452, 2014).
tumor (9 papers, 2011 to 2024). "FISH evidence for FRYL-SH2D1A indicates that at most one copy of the FRYL-SH2D1A fusion exists in the genome of each tumor cell, suggesting that amplification of the SH2D1A region is not the underlying cause of SH2D1A overexpression." (PMID 21625565, 2011). "We found that numerous NK cell effector function-related genes, such as TBX21, FYN, NCR1, SH2D1A, SH2D1B, PTPN6, and IL18RAP, were downregulated in tumor-infiltrating NK cells." (PMID 34535671, 2021).
infection (4 papers, 2013 to 2018). The state of being infected such as from the introduction of a foreign agent such as serum, vaccine, antigenic substance or organism. "The expression of SH2D1A reduced after stimulation compared with control in IR; we speculate that it may participate in activating the host immune response during infection." (PMID 30581844, 2018).
cancer (2 papers, 2022 to 2023). A tumor composed of atypical neoplastic, often pleomorphic cells that invade other tissues. "SH2 domain containing 1A (SH2D1A) expression has been linked to cancer progression." (PMID 37858067, 2023). "SH2D1A overexpression promotes cancer cell growth and metastasis via the Nf-κB signaling pathway and is significantly related to the immune microenvironment in HCC." (PMID 37858067, 2023). "In addition, SH2D1A mutations are associated with disease progression, while the roles of SH2D1A in HCC and other cancers have not been identified." (PMID 37858067, 2023).
SH2D1A also shares sentences with these, for which no sentence is quoted: hemophagocytic lymphohistiocytosis (5 papers); infectious mononucleosis (4); viral infections (4); agammaglobulinemia (3); Chédiak-Higashi syndrome (2); hematological malignancies (2); rheumatoid arthritis (2); Sepsis (2); Splenomegaly (2); acquired immunodeficiencies (1); autoinflammatory syndrome (1); breast carcinoma (1); Burkitt lymphoma (1); chronic granulomatous disease (1); common variable immunodeficiency (1); COVID-19 (1); diabetes (1); enteropathy (1); Epstein-Barr virus infection (1); experimental autoimmune encephalomyelitis (1); genetic disorders (1); glioma (1); Hemophagocytosis (1); Hepatosplenomegaly (1); hyperferritinemia (1); hypertriglyceridemia (1); Hypofibrinogenemia (1); juvenile idiopathic arthritis (1); Lymphadenopathy (1); Lymphoproliferative Syndrome Type 1 (1).
A further 16 diseases each share a sentence with SH2D1A in 1 paper.